BDNF (brain derived neurotrophic factor)
Diseases named in the same sentence as BDNF in open-access papers (continued):
Sharing a sentence is not in itself a finding about the gene and the disease.
schizophrenia (continued). "Findings suggest that fetuses who later go on to develop schizophrenia, compared to control fetuses, exhibit a reduced neurotrophic response to hypoxia (assessed through brain-derived neurotrophic factor levels in cord blood)." (PMID 41073801, 2026). "Emerging evidence suggests that patients with schizophrenia exhibit gut microbiota dysbiosis and decreased levels of short-chain fatty acids (SCFAs) and BDNF, which are related to the severity of psychotic and cognitive symptoms." (PMID 42022121, 2026). "Modulation of the brain-derived neurotrophic factor (BDNF) pathway is perceived as a promising neuroprotective strategy for preventing schizophrenia-related brain changes." (PMID 41169352, 2025). "Variations in BDNF levels and issues with BDNF signaling pathways have been connected to the development of schizophrenia." (PMID 40612741, 2025). "The results of this study showed that the combination of risperidone and MECT can better improve the levels of GFAP and BDNF in patients with schizophrenia." (PMID 41244550, 2025). "Although meta-analytic evidence consistently shows that peripheral BDNF levels are lower in schizophrenia compared to healthy controls, variability at the level of individual studies persists." (PMID 41008288, 2025). "Using RT-qPCR, mRNA levels of NURR1, BDNF, TrkB and p75 was quantified in schizophrenia (n = 65) and control (n = 64) ventral mesencephalon." (PMID 40335479, 2025). "Additionally, early trauma in schizophrenia patients is linked to reductions in monocytes, increased pro-inflammatory markers and reduced BDNF levels, reflecting a unique profile of changes associated with schizophrenia vulnerability that could stem from early developmental stages." (PMID 40335479, 2025). "In human midbrain, snRNAseq confirmed a primarily neuronal localization for BDNF expression in both low and high inflammation schizophrenia cases, as well as controls." (PMID 40335479, 2025). "Not only did it achieve positive results in the improvement of psychological symptoms and cognitive functions, but it also provided new insights into the biological mechanism of schizophrenia by regulating serum BDNF and S100B levels." (PMID 41312344, 2025). "Significant reductions in BDNF and TrkBTK+ (mRNA and protein) are present in multiple brain regions in schizophrenia, including the dorsolateral prefrontal cortex (DLPFC), anterior cingulate cortex and hippocampus." (PMID 40335479, 2025). "Given the limited research on the interplay between vitamin D and BDNF in schizophrenia, these results show a potential direction for future research." (PMID 40867540, 2025). "We find that reductions in trophic support proximal to midbrain dopamine neurons in schizophrenia include both the ligand and full-length receptor, with reduced BDNF and TrkBTK+ gene expression." (PMID 40335479, 2025). "Background/Objectives: Brain-derived neurotrophic factor (BDNF) is a neurotrophin critical for neurogenesis and synaptic plasticity, and alterations in its peripheral levels have been associated with schizophrenia and other psychotic disorders." (PMID 41008288, 2025). "The plasma level of BDNF is significantly reduced in patients with a first episode of schizophrenia compared to healthy people." (PMID 41007810, 2025). "Future studies should leverage these methods to characterize the extent to which BDNF trafficking is altered in schizophrenia." (PMID 41254423, 2025). "In this study, we observed that the expression of BDNF was significantly lowerin schizophrenia patients with clozapine-induced MetS compared to those withoutmetabolic syndrome." (PMID 41523972, 2025). "One cross-sectional study found a positive correlation between vitamin D and BDNF levels, with both displaying significantly lower levels in patients with schizophrenia compared to healthy controls." (PMID 40867540, 2025).
schizophrenia (continued). "Future studies investigating the impact of early life stress on BDNF and neuroinflammation in schizophrenia with larger cohorts are warranted." (PMID 40335479, 2025). "A comprehensive meta-analysis encompassing 2,667 patients and 2,580 controls revealed significantly lower peripheral BDNF levels in individuals with schizophrenia compared to healthy controls." (PMID 40082848, 2025). "Neurotrophins, particularly BDNF, are considered to play a key role in the pathophysiology of depression, stress, and schizophrenia." (PMID 40867109, 2025). "The psychotic symptoms, severity of schizophrenia symptoms, memory ability, cognitive function, serum BDNF, S100B, and GFAP levels, and incidence of adverse reactions between the two groups were compared." (PMID 41312344, 2025). "In animal models, decreased BDNF expression led to schizophrenia-like behavioral changes, including reduced social interaction and cognitive dysfunction." (PMID 40082848, 2025). "Beyond neurotransmitter systems, cognitive function in schizophrenia patients correlates with brain-derived neurotrophic factor (BDNF) levels." (PMID 40896216, 2025). "Significant associations were observed between chronic schizophrenia and reduced levels of NGF-β (B = 1.040, P < 0.001, RR = 2.829, 95% CI: 2.101−3.811) and BDNF (B = 0.526, P = 0.001, RR = 1.692, 95% CI: 1.241−2.306)." (PMID 40082848, 2025). "Further case-control studies on the BDNF gene and peripheral BDNF levels with larger sample sizes and different ethnic groups are needed to better understand the pathogenesis of the schizophrenia." (PMID 40458783, 2025). "Gene expression of the primary full-length neurotrophic receptor of BDNF, TrkBTK+, was also reduced in schizophrenia cases compared to controls by 18.5% [F(1116) = 19.768, p < 0.001]." (PMID 40335479, 2025). "Findings support the role of the BDNF in the pathophysiology of schizophrenia, PTSD, bipolar disorder, suicide attempts, vulnerability to stress, and anxiety disorder." (PMID 38928583, 2024). "A previous study has highlighted the significance of BDNF expression in the prefrontal cortex (PFC) of individuals with schizophrenia." (PMID 38592583, 2024). "For example, the ATAAT haplotype (5 SNP NTRK2) is associated with a reduced risk of schizophrenia in men, and the GTAGCC haplotype [5 SNP NTRK2 and 1 rs6265-C (V64V) SNP of the BDNF gene] is associated with a reduced risk of it in women." (PMID 38646100, 2024). "Investigations into the relationship between serum BDNF levels and brain volume changes in schizophrenia have been conducted." (PMID 39935805, 2024). "(2011) found that BDNF level is decreased in both drug‐naïve and drug‐exposed patients with schizophrenia." (PMID 38376038, 2024). "While the precise mechanisms are complex and still under investigation, it is evident that BDNF plays a role in the neurodevelopmental aspects of schizophrenia." (PMID 39568824, 2024). "BDNF's involvement in schizophrenia extends beyond mere reduction in levels; it is intertwined with the complex interactions within the brain regions involved in the disorder." (PMID 39568824, 2024). "BDNF plays a vital role in neurogenesis and synaptic connectivity in the brains of individuals with schizophrenia." (PMID 39935805, 2024). "Reduced BDNF levels have been observed in individuals with schizophrenia, contributing to the intricate neurobiological landscape of the disorder." (PMID 39568824, 2024). "Studies have indicated that individuals diagnosed with schizophrenia exhibit reduced blood levels of BDNF compared to healthy controls." (PMID 39064675, 2024). "This highlights the importance of considering both genetic and environmental factors in the study of how BDNF affects the pathogenesis of schizophrenia." (PMID 38673018, 2024). "BDNF levels have been shown to be markedly reduced in both plasma and postmortem brains of schizophrenia patients, suggesting that BDNF dysfunction plays a key role in the pathogenesis of this disease." (PMID 39012420, 2024).
schizophrenia (continued). "In patients with chronic schizophrenia, BDNF levels are closely related to memory, attention, information-processing speed, and cognitive impairment." (PMID 38203806, 2024). "The rs6265-T (V66M) variant in the BDNF gene, for instance, reduces inducible BDNF production and is associated with an elevated risk of MDD in the Mexican American population and paranoid schizophrenia in the Chinese population." (PMID 38699454, 2024). "For example, mood-stabilizing drugs such as lithium increase the expression of BDNF while, benzodiazepines reduce BDNF serum levels in patients with schizophrenia." (PMID 38006577, 2024). "BDNF has been proposed as a potential biomarker for schizophrenia, particularly in cognitive recovery." (PMID 39886050, 2024). "Evidence suggests that peripheral BDNF levels are generally lower in individuals with schizophrenia compared to healthy controls." (PMID 39935805, 2024). "Polymorphisms in BDNF and altered post-mortem BDNF brain levels have been identified in schizophrenia patients, and animal models have shown both decreased and increased BDNF levels in different brain regions." (PMID 39125882, 2024). "Given its importance in neuroplasticity and cognitive function, BDNF has become a focus of interest in psychiatric disorder research, especially schizophrenia." (PMID 38673018, 2024). "In both bipolar disorder and schizophrenia, there is a considerable decrease in the expression of BDNF and SPRY2, according to quantitative real-time polymerase chain reaction analysis of RNA in 100 individuals." (PMID 39456824, 2024). "Associations of rs6265 in BDNF, rs1800955 in DRD4, and rs6313 in HTR2A with schizophrenia in patients from the schizophrenia group separately compared to the control group were also found." (PMID 38397229, 2024). "Glial cell line-derived neurotrophic factor (GDNF) and brain-derived neurotrophic factor (BDNF) are two widely studied families of neurotrophins in schizophrenia." (PMID 39886050, 2024). "There is evidence that BDNF levels are changed in animal models of schizophrenia and other psychiatric disorders." (PMID 39012420, 2024). "Research has demonstrated that dopamine D1 receptor transmission in the dorsolateral prefrontal cortex is elevated in schizophrenia patients, regulating BDNF expression." (PMID 39125882, 2024). "In neurodevelopmental models of schizophrenia, alterations in BDNF levels are a recurring theme, suggesting a link between the characteristic cognitive dysfunction of this disease and the brain’s reduced capacity to adapt and respond to the environment." (PMID 38673018, 2024). "The development of the PNN depends on BDNF and JNK signaling, and disruptions in the PNN have been linked to schizophrenia." (PMID 39125882, 2024). "Previous findings indicated a decreased expression of TrkB and its natural agonist BDNF in patients with schizophrenia and their involvement in the pathophysiology of schizophrenia." (PMID 38277461, 2024). "After neuroplasticity-based cognitive training, serum levels of BDNF are significantly increased in patients with chronic schizophrenia." (PMID 39886050, 2024). "Research consistently indicates that peripheral BDNF levels are significantly lower in individuals with schizophrenia." (PMID 38615362, 2024). "Chronic high doses of haloperidol or risperidone are responsible for the downregulation of BDNF transcripts in the hippocampus, and a decrease in serum BDNF concentration is reported in patients affected by schizophrenia treated with clozapine." (PMID 36983018, 2023). "Some researchers pointed to a beneficial effect of BDNF on the severity of depressive symptoms in schizophrenia, which they link to the neuroprotective effect of this factor." (PMID 36979300, 2023). "The red cluster is the largest cluster with common keywords such as BDNF, neurotrophic factor, cognition, neuroplasticity, neurodevelopmental, and first-episode schizophrenia." (PMID 37077958, 2023).
schizophrenia (continued). "BDNF is also dysregulated in several psychiatric disorders, including bipolar disorder, schizophrenia, depression, and autism spectrum disorder." (PMID 37520481, 2023). "This study aimed to evaluate the contribution of BDNF gene variants (rs6265, rs962369) to the susceptibility of one-episode MDD, recurrent MDD, and schizophrenia." (PMID 37626739, 2023). "Top 10 with the highest link strength, citations, and the number of links in the BDNF and schizophrenia field." (PMID 37077958, 2023). "A total of 457 keywords were collected from our collection of 335 BDNF and schizophrenia publications." (PMID 37077958, 2023). "The findings revealed significantly lower median levels of BDNF (0.36 pg/ml) in patients with schizophrenia compared to both the control group (0.51 pg/ml) and the methamphetamine group (0.72 pg/ml)." (PMID 37520481, 2023). "In conclusion, the serum level of BDNF can be a useful marker for distinguishing between schizophrenia and methamphetamine addiction, particularly in cases where clinical differences are challenging to detect." (PMID 37520481, 2023). "Previous studies have shown delayed motor development and Brain-Derived Neurotrophic Factor (BDNF) level change in individuals with schizophrenia." (PMID 37234686, 2023). "The distribution of BDNF rs6265 genotypes and alleles was similar between controls and patients with recurrent MDD (F33) or schizophrenia (F20)." (PMID 37626739, 2023). "The BDNF dysfunctions were also reported in schizophrenia and schizoaffective disorder by other studies in the same cluster." (PMID 37077958, 2023). "Molecular Psychiatry is the most prestigious journal in the field of BDNF and schizophrenia research." (PMID 37077958, 2023). "BDNF (brain-derived neurotrophic factor) is one of the most-studied neurotrophic factors in schizophrenia." (PMID 37239308, 2023). "This study investigated the role of serum brain-derived neurotrophic factor (BDNF) levels in individuals with schizophrenia and methamphetamine addiction and their correlation with Mini-Mental State Examination (MMSE) scores." (PMID 37520481, 2023). "BDNF plays a role in many processes confirmed in the pathophysiology of schizophrenia, including the survival and plasticity of dopaminergic, cholinergic, and serotonergic neurons." (PMID 36831706, 2023). "This review aims to perform a bibliometric analysis of the research related to brain-derived neurotrophic factor (BDNF) in schizophrenia and offer suggestions for further work." (PMID 37077958, 2023). "Significant decrease in mRNA BDNF can be found in prefrontal cortex of patients suffering from schizophrenia." (PMID 36767478, 2023). "It is well‐known that BDNF can cross the blood‐brain barrier, In some case control studies, peripheral blood and cerebro spinal fluid (CSF) levels of the BDNF protein were also decreased in patients with schizophrenia." (PMID 37485797, 2023). "Other articles in the same cluster also reported the role of BDNF in the cognitive function of schizophrenia patients." (PMID 37077958, 2023). "Research on schizophrenia and BDNF has advanced significantly, particularly among experts connected to China and the USA." (PMID 37077958, 2023). "Schizophrenia is the most prevalent psychotic disorder therefore studies showcasing the role of BDNF in this particular group of disorders are mostly focused on it." (PMID 36767478, 2023). "In particular, we focused our attention on two subtypes of the glutamate receptor—NMDA (1, 2A, and 2B) and the neurotrophin BDNF, which play a critical role in mediating cognitive functions that are impaired in schizophrenia." (PMID 37240042, 2023). "At a cut-off value of BDNF=0.37 pg/ml, the sensitivity and specificity of BDNF in differentiating between schizophrenia and methamphetamine addiction were 84% and 70%, respectively." (PMID 37520481, 2023). "Recent studies on patients affected by schizophrenia have also detected a decrease in BDNF levels in CNS and peripheral serum samples." (PMID 37108250, 2023).
schizophrenia (continued). "The findings revealed significantly lower BDNF levels in patients with schizophrenia compared to both the control group and the methamphetamine group." (PMID 37520481, 2023). "The BDNF plasma levels were measured using ELISAs in 40 patients with diagnoses of schizophrenia and 14 subjects from the control group." (PMID 37445746, 2023). "In a word, genetic variation in BDNF plays an important role in the treatment response in patients with schizophrenia." (PMID 37485797, 2023). "It is important to note that research on peripheral BDNF levels in individuals with schizophrenia has yielded varied results." (PMID 37520481, 2023). "In a randomized control trial on 36 schizophrenia subjects, supplementation with 360 mg/day of a bioavailable formulation for 8 weeks reported 22% improvement in BDNF." (PMID 39081970, 2023). "There are conflicting reports on the relationship between BDNF serum levels in patients with schizophrenia." (PMID 36831706, 2023). "Decreased production of BDNF also correlates with cognitive dysfunctions (problems with memory and learning), neurodegeneration and the intensification of apoptosis observed in schizophrenia." (PMID 37685795, 2023). "The present study aimed to investigate the role of BDNF levels in individuals with schizophrenia and methamphetamine addiction, as well as their correlation with MMSE scores." (PMID 37520481, 2023). "Several studies revealed that patients with schizophrenia have relatively lower BDNF levels compared to healthy controls." (PMID 37685795, 2023). "Our meta-analysis showed that treatment with ECT therapy and antipsychotic medication increases serum BDNF levels in patients with drug-resistant schizophrenia compared to patients treated with medication only." (PMID 37685795, 2023). "Due to this, our study focuses mainly on the role of BDNF in schizophrenia; however, we decided to include our research on other psychotic disorders." (PMID 36767478, 2023). "These keywords indicate that the red cluster has publications that focus on the BDNF role related to the pathogenesis of schizophrenia." (PMID 37077958, 2023). "The BDNF and schizophrenia publications from 2018 to 2022 were evaluated by bibliographic coupling using the full counting approach." (PMID 37077958, 2023). "Our study has shown delayed motor development and changes in BDNF levels in schizophrenia, extending insight into the early identification of patients with schizophrenia versus healthy populations." (PMID 37234686, 2023). "Neurodevelopmental models have proposed that synaptic function is negatively affected when BDNF concentrations are reduced, altering neurotransmission and giving rise to symptoms seen in schizophrenia." (PMID 36980961, 2023). "The study on schizophrenia patients undertaking rTMS sessions applied to the supplementary motor area with serum BDNF levels that were measured at three points in time, alongside clinical assessment, by a psychiatrist and showed no significant findings." (PMID 36767478, 2023). "While most studies have reported decreased peripheral BDNF levels, some articles have reported elevated BDNF levels in individuals with schizophrenia." (PMID 37520481, 2023). "Research conducted so far has revealed a reduction in BDNF concentrations both in peripheral blood and in brain tissue (post-mortem studies) in patients with schizophrenia, when compared to healthy control subjects." (PMID 37685795, 2023). "Both articles discussed the changes in BDNF levels due to different factors in two different ethics i.e. Chinese and Japanese schizophrenia patients." (PMID 37077958, 2023). "The articles included in this meta-analysis showed that, in the pre-ECT measurement, serum BDNF was decreased in drug-resistant patients with schizophrenia in comparison to healthy controls, and these differences were statistically significant." (PMID 37685795, 2023).